LAG3 (lymphocyte activating 3)
Diseases named in the same sentence as LAG3 in open-access papers (continued):
Sharing a sentence is not in itself a finding about the gene and the disease.
relapsing-remitting multiple sclerosis (1 paper, 2025). The most common clinical variant of multiple sclerosis, characterized by recurrent acute exacerbations of neurologic dysfunction followed by partial or complete recovery. "Relapsing-remitting multiple sclerosis (RRMS) and T1D patients have a considerably low level of LAG-3+ CD4 and CD8 T cells." (PMID 41041324, 2025).
renal medullary carcinoma (1 paper, 2025). "RCC tumors have demonstrated an elevated LAG3 expression, with notable upregulation observed in histologic variants such as papillary RCC, SMARCB1-deficient renal medullary carcinoma, and translocation RCC." (PMID 39858107, 2025).
Salmonella Infections (1 paper, 2025). Infections with bacteria of the genus SALMONELLA. "Following Salmonella infection, Lag3+CD138+ cells are found in the spleen, which also highly express IL10106." (PMID 41177809, 2025). "Functionally, Lag3+ plasma cells influence host resistance against Salmonella infection through IL10 production." (PMID 41177809, 2025).
secondary progressive multiple sclerosis (1 paper, 2019). A multiple sclerosis with a clinical course characterized by a progressive accumulation of neurological disability, independent of relapses, following an initial relapsing-remitting (RR) phase. "Moreover, CCR9+ memory T cells in CSF of patients with secondary progressive multiple sclerosis expressed high level of LAG3 and RORγt." (PMID 31354747, 2019).
serous carcinoma (1 paper, 2025). "However, in a cohort of chemotherapy-naïve high-grade serous carcinoma patients, tumor-infiltrated T cells expressing PD-1, LAG-3, and CTLA-4 were linked to favorable relapse-free survival and OS, whereas TIM-3+ cells were associated with reduced OS." (PMID 41221283, 2025).
serous cystadenocarcinoma (1 paper, 2025). A malignant serous cystic neoplasm usually involving the ovary or the pancreas. "Our findings reveal that the co-expression of PD-1 and LAG-3 serves as the optimal combination for predicting poor prognosis in OC patients, especially in patients with serous cystadenocarcinoma." (PMID 40895577, 2025).
Stroke (1 paper, 2025). Sudden impairment of blood flow to a part of the brain due to occlusion or rupture of an artery to the brain. "Other inhibitory checkpoint pathways such as PD-1, TIM-3, LAG-3, and TIGIT likely contribute to T cell regulation after stroke but were beyond the scope of this focused analysis and should be addressed in future studies." (PMID 41373643, 2025).
systemic sclerosis (1 paper, 2023). A chronic disorder, possibly autoimmune, marked by excessive production of collagen which results in hardening and thickening of body tissues. "The decreased frequency of LAG3+ B cells might contribute to increased apoptosis, which was seen in memory Breg cells in patients with systemic sclerosis." (PMID 37143367, 2023).
Tauopathies (1 paper, 2024). "This indicates varying binding affinities between Tau PFF from distinct Tauopathies and Lag3." (PMID 38327094, 2024). "The interaction between Lag3 and Tau PFF provides a new target for therapeutic development in AD and related Tauopathies." (PMID 38327094, 2024).
thymic carcinoma (1 paper, 2024). Thymic carcinoma (TC) is a type of thymic epithelial neoplasm characterized by a high malignant potential. "For thymic carcinoma, the novel biomarkers of MSLN, CCL20, and SLC1A5 are identified and observed an elevated expression of LAG3 and HAVCR2 in malignant tumorn‐infiltrating mature T cells." (PMID 39258580, 2024).
tongue tumors (1 paper, 2019). "Moreover, we observed that mEER tongue tumors were relatively resistant to α-Lag3 monotherapy as compared to α-PD-1 or α-CTLA-4." (PMID 31533840, 2019). "In addition to the differential PD-1 expression in tongue- and flank-implanted mEER tumors, CD8+ T cells from tongue tumors showed higher levels of additional immune checkpoint inhibitory molecules, CTLA-4 and Lag3." (PMID 31533840, 2019).
type IV hypersensitivity reaction (1 paper, 2023). "Since most T cell-driven animal systemic arthritis models are highly similar to a type IV hypersensitivity reaction without the formation of anti-CCP antibodies and IgM-RF, we turned to an ex vivo model to further investigate the function of LAG-3 in RA." (PMID 37287025, 2023).
uveitis (1 paper, 2021). An inflammatory process affecting a part of or the entire uvea. "(ii) i35-Exosome therapy: i35-Exosomes suppress uveitis by upregulating inhibitory receptors (PD1, LAG3), propagating infectious-tolerance signals which induced conventional lymphocytes to acquire capacity for producing immunosuppressive cytokines." (PMID 33995347, 2021).
viral hepatitis (1 paper, 2023). An acute or chronic inflammation of the liver parenchyma caused by viruses. "Our data suggest that combining the LAG-3+ or LAG3+CD8+ cell proportions with the CD38+ or CD38CD68+ cell proportions is more useful in patients with viral hepatitis, whereas the LAG-3+ and CD8+ cell proportions may be more useful in patients without viral hepatitis." (PMID 37342338, 2023). "After performing separate analyses of viral-related and non-viral HCC, we found that only the LAG-3+CD8+ cell proportion predicted responses to ICB regardless of the viral hepatitis status, with the overall best ORRs in both groups." (PMID 37342338, 2023).
tumor (2,274 papers, 2007 to 2026). "USP7 promotes immune suppression by stabilizing checkpoint molecules such as PD-L1, modulating FGL1/LAG-3 signaling, reshaping tumor-associated macrophage polarization, and reinforcing T-cell dysfunction." (PMID 42245660, 2026). "PD1 expression (in TILs and tumor cells) is associated with prolonged OS, while LAG3 expression (in tumor cells) is associated with shorter DFS and its expression in TILs tended towards shorter OS." (PMID 40481915, 2025). "Other inhibitory checkpoints implicated in NK cell tumor immunity include LAG-3, NKG2A, TIM-3, and TIGIT." (PMID 40849493, 2025). "Given the association between high LAG3 expression and favorable prognosis, these T cells likely possess enhanced anti-tumor capabilities." (PMID 40411616, 2025). "Elevated CTLA4 and LAG3 expression reflects increased immune checkpoint activity, likely contributing to T cell exhaustion and immune suppression in the tumor microenvironment of high-risk patients." (PMID 40243888, 2025). "The tumor microenvironment of OCCC is highly immunosuppressive, with infiltration of regulatory T cells, tumor-associated macrophages, and upregulation of immune checkpoint molecules, such as PD-1, PD-L1, and LAG-3." (PMID 41383608, 2025). "LAG3 expression in tumor cells was significantly associated with shorter disease-free survival (DFS)." (PMID 40481915, 2025). "The expression of LAG-3 has been observed in immune cells associated with ocular diseases, particularly in immune dysregulation within tumor microenvironments or inflamed tissues, which contributes to immune evasion." (PMID 41268982, 2025). "Research indicates that the upregulation of TIGIT and LAG-3 is closely associated with immune evasion and tumour resistance." (PMID 40861435, 2025). "Concurrent chemoradiotherapy without combined immunotherapy inhibited tumor-infiltrating T cells to a certain extent, and elevated immune checkpoint LAG3 was closely associated with immune activation in the ESCC tumor microenvironment." (PMID 40411616, 2025). "In active TIME, increased cytotoxic activity triggers negative feedback mechanisms that upregulate inhibitory checkpoints, such as PD-L1 and LAG-3, creating a hallmark"hot tumor"signature of concurrent high-level of cytotoxic and immunosuppressive markers." (PMID 40973957, 2025). "In vivo assays revealed that treatment with Lag-3 antibodies negated the tumor growth enhancement associated with Dcdc2 overexpression, while Fgl1 knockdown blocked the efficacy of Lag-3 antibodies." (PMID 40533767, 2025). "A previous study demonstrated functional synergy of PD-1 and Lag3 in the control of anti-tumour immunity, and this was linked to increases in IFN-gamma-expressing cells amongst both CD4+ and CD8+ T cells." (PMID 40351814, 2025). "Our data showed that LAG3 is highly upregulated in tumor-infiltrating iNKT cells and is associated with worse clinical outcomes, sustaining the targeting of LAG3 together with iNKT cell agonists." (PMID 41562072, 2025). "Concurrently, lymphocytes that infiltrate the tumor often show increased levels of immune checkpoint proteins, including lymphocyte-activation gene 3 (LAG-3), cytotoxic T-lymphocyte-associated protein 4 (CTLA-4), and programmed death 1 (PD-1)." (PMID 40805123, 2025). "The mutation rate for PDCD1 was 17%, and for LAG3 it was 17% and 13%, respectively, in both tumor types." (PMID 40076932, 2025). "ICIs act inhibiting tumor immune escape by targeting PD-1 and its ligand (PD-L1), lymphocyte-activating gene-3 (LAG3), cytotoxic T lymphocyte-associated antigen-4 (CTLA-4), and other targets." (PMID 40944286, 2025). "As an inhibitory immune checkpoint, high expression of LAG3 is associated with a positive response to immunotherapy due to its impact on the cytotoxic activity of immune cells against tumor cells." (PMID 38277212, 2024).
tumor (continued). "The up-regulation of Tbet transcription, which in turn inhibits PD-1 and LAG-3 transcription, has been suggested as the molecular mechanism underlying the anti-tumor activity of GSK-3 inactivation or deletion in T cells." (PMID 38175205, 2024). "While its signaling mechanisms and the extent of its expression patterns remain an active area of investigation, LAG-3 is often implicated in tumor-mediated immunosuppression and immune cell homeostasis." (PMID 38349406, 2024). "Despite these advances, the precise mechanisms underlying the LAG-3 effect in the tumor setting must still be elucidated." (PMID 39684559, 2024). "Like PD-1 and CTLA-4, continuous tumor-associated antigens exposure can result in high and sustained expression of LAG-3 on CD4+ and CD8+ T cells, which negatively regulate T cell expansion and lead to immune disorders, mainly manifested as T-cell exhaustion." (PMID 39252941, 2024). "In consideration of the significance of mutational burden in immunotherapy, we analyzed the correlation between LAG3 expression and Tumor Mutational Burden (TMB) as well as Microsatellite Instability (MSI)." (PMID 38277212, 2024). "A recent study demonstrated that CD8+ T cells deficient in both PD-1 and LAG-3 exhibited enhanced tumor clearance and improved long-term survival compared to those lacking either PD-1 or LAG-3 alone." (PMID 39839672, 2024). "LAG3 exhibited positive associations with key receptors involved in the recruitment of effector tumor-infiltrating immune cells (TIICs), such as CVCR3-CVCR6, as well as chemokines including CCL3-CCL5 and CXCL9-CXCL13." (PMID 38277212, 2024). "In KIRC, infiltration by C1q-producing TAMs was associated with an immunosuppressed tumor microenvironment, characterized by high expression of immune-checkpoint molecules (PD-1, LAG-3, PD-L1, and PD-L2)." (PMID 39697348, 2024). "Aberrant LAG-3 expression has been identified in various solid tumors, with its expression significantly associated with aggressive tumor progression and clinicopathological characteristics." (PMID 38785789, 2024). "Based on this strategy, one potential alternative approach is to inject anti-LAG-3 mAbs directly into the tumor with therapies targeting tumor-associated antigens (TAA)." (PMID 39660130, 2024). "LAG-3: LAG-3 is encoded by the LAG-3 gene and is expressed on the cell surface of natural killer cells (NK cells), B cells cells, tumor-infiltrating lymphocytes (TILs), and a subset of T cells, as well as dendritic cells (DCs)." (PMID 39594765, 2024). "Burugu and colleagues also found that elevated LAG-3 expression is strongly associated with higher tumor grades, larger tumor size, and HER2+ and basal-like BC." (PMID 37509517, 2023). "Lymphocyte-activation gene 3 (LAG3) is located on chromosome 12 (12p13.32) and encodes a type 1 transmembrane protein involved in tumor immune regulation and clinical aggressiveness." (PMID 38115039, 2023). "ORR was at least 3.5-fold higher in patients with LAG-3 expression in at least 1% of tumour-associated immune cells within the tumor margin (n = 33) than that in the patients with less than 1% LAG-3 expression (n = 22) (18% and 5%, respectively)." (PMID 36445478, 2023). "HIF-1α also stimulates the expression of the immune checkpoint inhibitors PD-L1, CTLA-4, and LAG-3 on tumor and tumor-associated immune and stromal cells." (PMID 37239368, 2023). "In this retrospective study of GC, we demonstrated the distribution patterns of LAG3 + cells within tumor tissues and their association with clinicopathological data and survival." (PMID 37311986, 2023). "Based on the inhibitory role of LAG3 in anti-tumor responses, several studies have focused on the association between LAG3 rs3782735A/G genetic polymorphisms and cancer risk development." (PMID 37131179, 2023). "Studies have reported that binding to its ligand LAG-3 can induce the suppression of T-cell and thus causing tumor evasion." (PMID 37927462, 2023).
tumor (continued). "LAG3 binds to Galectin-3 (GAL-3) with strong affinity and chronic LAG3 engagement on CD8+ tumor antigen-specific T cells has been implicated in exhaustion of TILs and reduction in their cytolytic capacity." (PMID 38086828, 2023). "Available data suggest that overexpression of LAG-3 on TILs is associated with high pathological grade, larger tumor size, and positive lymph nodes." (PMID 37509517, 2023). "For example, tumor-intrinsic protein and LAG3 mRNA expression are linked to methylation regulation in KIRC." (PMID 38041068, 2023). "Longer median immune-related response progression-free survival (irPFS) and higher ORR were associated with the presence of CD8+ tumor-infiltrating cells that express PD-1 but lack LAG3 and TIM3 and are more likely to be T cell activated." (PMID 37842234, 2023). "Both the predominant location of tumor-associated macrophages in the outer section of the tumor and the high presence of LAG-3 and Galectine-3 in the UM serve as attainable therapeutic targets." (PMID 37237550, 2023). "LAG3 expression in both compartments was associated with PD-L1 expression in tumor cells (p = 0.040, TC, and p = 0.001, IM)." (PMID 37311986, 2023). "LAG-3 expression was mostly associated with poor clinicopathological associations and outcomes, including tumor progression, resistance, and metastasis." (PMID 37509517, 2023). "Higher expression of LAG-3 and infiltration of LAG-3+ cells in tumors are associated with poor prognosis, tumor progression, and unfavorable clinical outcomes in various indications of cancer." (PMID 37304291, 2023). "Markers of CTL exhaustion such as HAVCR2 (encoded by the Havcr2 gene) and LAG3 (encoded by the Lag3 gene) increased over this period, suggesting that CTLs had become exhausted inside the tumor." (PMID 37182110, 2023). "The positive expression of LAG-3 in tumor cells is associated with high levels of CD8+ T cell immune infiltration." (PMID 37927462, 2023). "The authors observed that high LAG-3 expression on T cells was significantly associated with a decreased T cell production of anti-tumor TNF-α." (PMID 37520544, 2023). "At the same time, the expression levels of cytokines and immunosuppressor molecules (PD1, PD-L1, PD-L2, CTLA4, TIGIT, TIM-3, BTLA, and LAG3) were significantly higher in low-risk groups, implying more tumor immunogenicity in the low-risk group." (PMID 36217201, 2022). "In immune-inflamed LUSCs, LAG-3 demonstrated a significantly higher level than other genes known to inhibit the anti-tumor immune response and was associated with poor prognosis." (PMID 36077354, 2022). "LAG-3 highly expressed on the TILs interacts with ligands located on the surface of tumor cells to cause T cell dysfunction or even exhaustion, promoting tumor immune escape, the phenomenon of which is particularly evident in CD8+ T cells." (PMID 35958563, 2022). "It was discovered that IP-score was closely associated with PDCD1, CD274, CTLA-4, and LAG3 expression levels in urinary solid tumours, indicating that IP-score was closely associated with tumour escape and immune depletion." (PMID 36700205, 2022). "Next, we analyzed the relationship between risk score and different tumor stages, clusters, and the expression level of m6A methylation genes and LAG3." (PMID 36051357, 2022). "In contrast, lymphocyte-activation gene 3 (LAG3) immune checkpoint protein was shown to be highly expressed on tumor-infiltrating CD8+ T cells of high-risk primary UM and was associated with worse survival in UM." (PMID 35267523, 2022). "The high expression of LAG3 has been associated with unfavorable clinical outcomes in various tumor types including NSCLC." (PMID 36568253, 2022). "Inhibitory immune checkpoint molecules, including PD-1, CTLA4, and LAG3, are abundantly expressed on the surface of tumor-infiltrating lymphocytes, thus causing susceptibility to inhibitory signals from the TME." (PMID 36292781, 2022).